CWC22 (CWC22 spliceosome associated protein)
Description:
Required for pre-mRNA splicing as component of the spliceosome. As a component of the minor spliceosome, involved in the splicing of U12-type introns in pre-mRNAs (Probable). Promotes exon-junction complex (EJC) assembly. Hinders EIF4A3 from non-specifically binding RNA and escorts it to the splicing machinery to promote EJC assembly on mature mRNAs. Through its role in EJC assembly, required for nonsense-mediated mRNA decay.
Synonyms: KIAA1604; NCM; EIF4GL; fSAPb
Tractability: Small molecule: a structure with a bound ligand is known. PROTAC: ubiquitination databases record sites on it; its protein half-life has been measured.
Gene: Protein-coding gene on chromosome 2 (179,944,872 to 180,007,297, reverse strand). Ensembl gene ENSG00000163510.
Subcellular location: Nucleus; Nucleus speckle
Subcellular location (Human Protein Atlas): Nuclear speckles; Cytosol
Pathways (Reactome):
Disease: Dengue Virus-Host Interactions
Metabolism of RNA: mRNA Splicing - Major Pathway
Gene Ontology:
Molecular function: protein binding; RNA binding
Biological process: mRNA splicing, via spliceosome; regulation of mRNA splicing, via spliceosome
Cellular component: catalytic step 2 spliceosome; nuclear speck; nucleus; post-spliceosomal complex; spliceosomal complex; U12-type catalytic step 2 spliceosome; U2-type catalytic step 1 spliceosome; U2-type catalytic step 2 spliceosome; U2-type precatalytic spliceosome; nucleoplasm
Genetic constraint (gnomAD): Loss-of-function variants: 32 observed, 49.11 expected, observed/expected ratio (o/e) 0.65, 90% interval 0.49 to 0.88. The upper end of that interval is the gene's LOEUF score, 0.88, which puts it in group 3 of 6, group 1 being the genes least tolerant of losing a copy. Missense variants: 587 observed, 654.8 expected, observed/expected ratio (o/e) 0.9, 90% interval 0.84 to 0.96. Synonymous variants: 209 observed, 221.99 expected, observed/expected ratio (o/e) 0.94, 90% interval 0.84 to 1.06.
Homologues: Orthologues: chimpanzee CWC22 (99% identical), macaque CWC22 (97% identical), dog CWC22 (93% identical), pig CWC22 (92% identical), rat LOC134479418 (85% identical), mouse Cwc22 (84% identical), mouse Cwc22rt1 (77% identical), mouse Cwc22rt2 (77% identical), mouse Cwc22rt3 (77% identical), mouse Cwc22rt4 (77% identical), mouse Cwc22rt5 (77% identical), mouse Cwc22rt6 (77% identical), and 6 more. Paralogues in human: NOM1 (15% identical).
Diseases named in the same sentence as CWC22 in open-access papers:
CWC22 is named in the same sentence as 17 diseases in open-access papers, as found by Europe PMC text mining. Sharing a sentence is not in itself a finding about the gene and the disease. The quoted sentences say what the papers report.
colon cancer (2 papers, 2020 to 2021). "Survival analysis using selected hub genes, such as AHSA2, CDK10, and CWC22, showed that their expression levels were significantly associated with the survival rate of colon cancer patients, which indicates their possible use as prognostic markers." (PMID 32345988, 2020). "In conclusion, using a gene expression network analysis, we have identified hub genes, such as AHSA2, CDK10, and CWC22, as being possible prognostic markers, that were not previously known to be associated with colon cancer." (PMID 32345988, 2020).
diabetes (2 papers, 2017 to 2024). "Inhibition of a key splicing factor, CWC22, that is aberrantly upregulated in diabetes and impacts the growth properties of sensory neurons, improves features of DPN." (PMID 28250049, 2017). "Included among those upregulated in diabetes was Cwc22, an mRNA splicing factor located in nuclear speckles." (PMID 28250049, 2017). "In keeping with this, our DRG mRNA array did identify aberrant CWC22, an essential splicing factor in diabetes." (PMID 28250049, 2017). "The research also referred to changes in global gene expression within the dorsal root ganglion (DRG) sensory neurons in diabetes, introducing differentially expressed mRNAs and their potential therapeutic implications, such as CWC22 and DUSP1, in improving neuropathic features in diabetes." (PMID 38928135, 2024). "To examine whether inhibition of CWC22 upregulation in diabetes could alter the diabetic phenotype, we utilized local nonviral siRNA to downregulate its expression unilaterally in the hindlimb of diabetic and nondiabetic mice in vivo." (PMID 28250049, 2017).
diabetic polyneuropathy (2 papers, 2017 to 2021). "Overall, the findings did identify selective improvements by Cwc22 mRNA knockdown on established abnormalities of a chronic diabetic neuropathy model." (PMID 28250049, 2017). "Interestingly, the overexpression of Cwc22 was also observed in sensory neurons of diabetic mice, where it was found to act as a mediator of diabetic polyneuropathy." (PMID 35008877, 2021).
cervical cancer (1 paper, 2026). A primary or metastatic malignant neoplasm involving the cervix. "Public datasets showed that CWC22 was highly expressed in pancreatic or cervical cancers, and higher expression negatively correlated with patient prognosis." (PMID 41534835, 2026).
polyneuropathy (1 paper, 2017). A disease or disorder affecting more than one nerve. "Collectively, our findings identify subtle but significant alterations in spliceosome structure and function, including dysregulated CBs and CWC22 overexpression, in diabetic sensory neurons that offer new ideas regarding diabetic sensory neurodegeneration in polyneuropathy." (PMID 28250049, 2017).
retinal degeneration (1 paper, 2021). Degeneration of the retina. "The most upregulated gene in the neuroretina of Gnat1rd17 mice, Cwc20, was a CWC22 spliceosome-associated protein that functions as the major partner of CWC27 (CWC27 spliceosome-associated cyclophilin), a splicing factor linked to retinal degeneration and other developmental defects." (PMID 35008877, 2021).
testicular germ cell tumor (1 paper, 2025). A germ cell tumor arising from the testis. "This region, commonly altered in several cancer types (especially testicular germ cell tumors), contains four NMD-related genes (CWC22, SF3B1, NOP58, and FARSB)." (PMID 41023738, 2025).
viral infections (1 paper, 2021). "Four additional positional candidate genes, carbonic anhydrase 10 (CA10), CWC22 spliceosome-associated protein (CWC22), DISC1 scaffold protein (DISC1), and nitric oxide synthase 1 adaptor protein (NOS1AP), have roles in pulmonary dysfunction, viral infections, or both." (PMID 34409086, 2021).
cancer (4 papers, 2022 to 2026). A tumor composed of atypical neoplastic, often pleomorphic cells that invade other tissues. "Targeting CWC22 induced cancer cell death following mitotic slippage and a prolonged G2 phase because of DNA damage accumulation." (PMID 41534835, 2026). "Our study reveals a more complex picture in cancer, where chromosomal gains containing various splicing factors (1q gain: SF3B4, PRPF3, 2q gain: CWC22, SF3B1) and other NMD-related genes are associated with reduced NMD efficiency." (PMID 41023738, 2025).
infection (1 paper, 2021). The state of being infected such as from the introduction of a foreign agent such as serum, vaccine, antigenic substance or organism. "However, a study on how influenza viruses, like H1N1, harness host cells' ability to replicate during respiratory illness found that the expression of CWC22 was linked with a decreased cellular infection rate." (PMID 34409086, 2021).
CWC22 also shares sentences with these, for which no sentence is quoted: cardiac hypertrophy (1 paper); gout (1); liver cancer (1); neurodegenerative disease (1); neuropathy (1); prostate carcinoma (1); schizophrenia (1).